HK1 (hexokinase 1)
Diseases named in the same sentence as HK1 in open-access papers (continued):
Sharing a sentence is not in itself a finding about the gene and the disease.
tumor (continued). "Combined, the present study suggests the glycolysis-independent role of HK1 in tumor progression, which is involved in metformin resistance of the tumors." (PMID 34895333, 2021). "Oncogenic KRAS is known to regulate metabolism in the tumor environment increasing glucose uptake and glycolysis by directly regulating HK1 activity and increasing LDHA expression." (PMID 34120142, 2021). "LINC00470 can also enhance the activity of AKT while inhibiting the ubiquitination of HK1, thereby inhibiting the autophagy of tumour cells while promoting tumorigenesis." (PMID 33749070, 2021). "Consistently, we observed little effects of the HK1 or HK2 deletion in vitro; however, the HK1 deletion substantially delayed the tumor growth in vivo." (PMID 34895333, 2021). "Theoretically, all hexokinase isozymes (HK1 to HK4) should be highly expressed for tumor initiation and maintenance." (PMID 32802843, 2020). "The predominant role of HK2 in tumor cells is also confirmed by the observation that the tumor subgroups expressing both HK1 and HK2 are sensitive to inhibition of HK2 alone." (PMID 33008042, 2020). "Except the expression of HK1 was downregulated, the other seven genes were significantly upregulated in tumor tissues (P < 0.05)." (PMID 33029143, 2020). "While hexokinase 1 normally phosphorylates glucose on cell entry, in tumor cells hexokinase 2 has been shown to be crucial for the Warburg effect, i.e. a shift to aerobic glycolysis for ATP production, irrespective of the availability of oxygen." (PMID 32997701, 2020). "At the 11st day after injection, the ratios of mice with detectable tumor are 5/5 and 2/5, respectively for HK1-CON and HK1-DHRS2 groups." (PMID 31291971, 2019). "Since HK1 knockdown induces tumor malignancy via deregulation of energetic metabolism from aerobic respiration to glycolysis, the commonly used glycolytic inhibitor 2-DG is thus a potential chemotherapeutic agent for HK1-silenced cells." (PMID 29721175, 2018). "HK1, which we found overexpressed in embryonal compared to fetal‐like tumor cells, is abundant in the developing liver, with levels dramatically reduced at birth." (PMID 28923827, 2017). "Substitution of intracellular HK1 with HK1-Y732F prominently impeded xenograft tumour growth and the tumours containing HK1-Y732F displayed decreased HK activity and lactate production versus that expressing WT HK1." (PMID 28054552, 2017). "Our results suggest HK1 and HK2 as key enzymes for glucose metabolism associated with survival of tumor cells." (PMID 28105937, 2016). "Relationships between GLUT1, HK1, PKM2, and LDHA immunohistochemical expression and GIST tumor risk grade." (PMID 26509967, 2015). "Our results showed that 18F-FDG uptake correlates with tumor size, tumor risk grade, and expression levels of GLUT1, HK1, and LDHA." (PMID 26509967, 2015). "We found that 18F-FDG uptake correlated positively with tumor size, risk grade, and expression levels of glucose transporter 1 (GLUT1), hexokinase 1 (HK1), and lactate dehydrogenase A (LDHA)." (PMID 26509967, 2015). "The increased expression of GLUT1, HK1, PKM2, and LDHA with higher tumor risk grades indicates important roles for these proteins in GIST tumorigenesis and suggests their usefulness in the preoperative prediction of malignant potential." (PMID 26509967, 2015). "In vitro studies on two different cell lines derived from Imatinib-resistant or Imatinib-sensitive tumours showed the common expression of hK1." (PMID 20859288, 2010). "ANOVA detected a difference in hK1 expression with regard to the tumour location (P=0.02), with largest positive areas in small intestine samples (18.6±4.7% of total section), followed by the stomach (9.1±2.4%) and rectum (2.9±2.2%)." (PMID 20859288, 2010).
tumor (continued). "HIF-1α switches metabolisms in tumor by upregulating the transcription of enzymes of glycolysis, such as hexokinase 1/2 (HK I/II) and pyruvate kinase isoenzyme M2 (PKM2), glucose transporters (Glut) such as Glut-1 and 3, alongside other genes inhibiting oxidative phosphorylation." (PMID 36045917, 2022). "However, the glycolytic capacity of HK1-ablated cells was significantly lower compared to control, indicating that tumor cells have low dependence on glycolysis." (PMID 36291051, 2022). "This lEV HK1 is taken up by HCC cells to facilitate tumor growth through glycolytic reprogramming." (PMID 36192599, 2022). "Thus, in Hk1f/f;Gfap-Cre mice, the growth of Hepa1-6-derived orthotopic xenografts and the expression of HK1 and Ki67 in tumor tissues were substantially decreased compared with those in Hk1f/f mice." (PMID 36192599, 2022). "Therefore, HK1 is involved in yet undescribed nutrient-sensing and acquisition mechanisms with the capacity to shape the metabolic landscape of the tumor microenvironment." (PMID 34895333, 2021). "Upon binding, K-Ras4A blocks the allosteric inhibition of HK1 resulting in an enhanced glucose consumption, which might contribute to the metabolic reprogramming of tumor cells aimed to sustain rapid tumor growth." (PMID 33816563, 2021). "However, a study showed that HK2 was upregulated but HK1 was downregulated to increase glycolysis and accelerate tumor growth and metastasis." (PMID 32802843, 2020). "In this study, we demonstrated that HK1 knockdown not only impairs energetic metabolism, including respiratory dysfunction and increased glycolysis, but also causes an EMT switch and consequently accelerates tumor malignancy." (PMID 29721175, 2018). "Knockdown of HK1 significantly slowed down xenograft tumour growth in nude mice." (PMID 28054552, 2017). "shHK1-mediated knockdown of HK1 in HCT116 cells significantly decreased the number of metastatic tumour nodules on the surface of lungs, in comparison with control cells expressing shGFP indicating that HK activity is essential for metastatic ability of HCT116 cells." (PMID 28054552, 2017). "SUVmax correlated with tumor size; expression of GLUT1, HK1, and LDHA; and NIH risk group." (PMID 26509967, 2015). "Therefore, it is not surprising that proliferative state and the glycolysis associated genes GLUT1, HK1 and HK2 cannot alone explain the FDG uptake in the tumor tissue." (PMID 26824929, 2013). "In particular, hK1 was expressed in the central core and the peripheral part of the tumour." (PMID 20859288, 2010). "It is therefore likely that changes in hK1 production, release and clearance by endogenous inhibitors may confer a different invasive profile to the tumour." (PMID 20859288, 2010). "Our in vitro data show that expression levels in the GIST cell line are increased by hypoxia/starvation, pointing to the possibility that areas of the tumour far away from the vasculature could be stimulated to produce larger amounts of hK1." (PMID 20859288, 2010). "Similarly, circulating levels of hK1 increased in tumour-bearing mice in proportion to tumour size, being detectable even in the smallest dosage of GIST882 cells." (PMID 20859288, 2010). "Similarly, HK1, a key regulatory metabolic marker for glycolysis and tumor metastasis, was downregulated in the brain tissue of exposed chicken embryos; however, its expression was upregulated in the heart of the exposed embryos, indicating a possible cardioprotective effect of the treatments." (PMID 34681694, 2021). "Metformin can block tumor progression induced by inflammasome activation in tumor-infiltrating immune cells, protect the intestinal barrier from the LPS-triggered damage by alleviating NF-κB phosphorylation, and directly inhibit the enzymatic activity of HK1 and HK2." (PMID 33980323, 2021). "Using cell lines and primary cultures of GBM, we showed that inducible knockdown of HK2 altered tumor metabolism, which could not be recapitulated by HK1 or HK3 loss." (PMID 27588472, 2016).
tumor (continued). "HK1 was overexpressed in 30% of CRC cases, and significantly correlated with advanced tumour stages and poorer overall survival." (PMID 41154605, 2025). "Volcano plot analysis of differentially expressed genes showed that NDRG1 is markedly upregulated in tumor tissues, alongside several key metabolic genes, including LDHA, SLC16A1, PKM, HK1, and LDHB." (PMID 40539245, 2025). "While HK1 transcript remained similar in both tissue types, HK2 expression was 35% lower in CRC tumours." (PMID 40045444, 2025). "Glycolysis genes HK1, GAPDH, ENO1, LDHA, and PKM, and cell cycle genes (except CCND2) were among the most tumor-specific genes." (PMID 39774001, 2025). "Mammals express four hexokinase (HK) isoforms (HK1, HK2, HK3, and HK4), among which HK2 is markedly upregulated in tumor tissues compared to normal counterparts." (PMID 40756987, 2025). "For example, in pancreatic cancer, inhibiting the expression of NR3C2 leads to the upregulation of glycolytic enzymes HK1, HK2, and LDHA, promotes glucose uptake and lactate production and accelerates tumor growth." (PMID 41219936, 2025). "Many miRNAs target HK1 or HK2 to affect glucose metabolism in CRC and interfere with tumor proliferation." (PMID 37576895, 2023). "The expression levels of key glycolytic enzymes, namely GLUT1, ENO1, PGK1, ALDOA, HK1, and LDHA, in the tumor tissues of chemotherapy-resistant and chemotherapy-sensitive groups were examined using IHC analysis." (PMID 34510316, 2022). "Upregulation of GLUT1, HK1, pyruvate kinase-M2 splice isoform, and LDHA enhances the Warburg effect in tumor cells." (PMID 35310040, 2022). "Western blot showed that a decrease in the expression levels of PKM2, GLUT-1, HK1, HK2, PKM1, and LDHA decreased in tumor cells and an inhibition of glycolysis and cell proliferation." (PMID 36284386, 2022). "In most cancers, HK1 and HK2 have the highest affinity for glucose transporters and are thought to play important roles in the regulation of antitumor efficacy and tumor prognosis." (PMID 36276846, 2022). "PPI showed that HK2 was closely related to HK1, GPI, and HK3, all of which played an important role in tumor proliferation." (PMID 34708035, 2021). "HK1, HK3, and GPI are all key genes in glycolysis, which can promote the proliferation and development of tumor cells by promoting the glycolysis effect of tumor cells." (PMID 34708035, 2021). "The decreased expression of Hif-1α and its downstream effectors, including HK1, HK2, PKM1, and PKM2 in PD901 treated tumor cells was further confirmed by Western blotting (Sup." (PMID 30741922, 2019). "Four enzymes from glycolysis were included: hexokinase (HK1), phosphoglucose isomerase (PGI), phosphofructokinase (PFKM), pyruvate kinase (PKM2, the major isoform in tumours) and lactate dehydrogenase (LDHA)." (PMID 30655616, 2019). "Substitution of cellular HK1 or HK2 with their corresponding mutants significantly diminishes c-Src stimulated glucose uptake, retarded proliferation and dampened xenograft tumour growth in nude mice." (PMID 28054552, 2017). "Taken together, when tumour cells are rich for glucose, both HK1 and HK2 are essential for c-Src stimulated maximum glucose flux required for rapidly proliferating tumour cells." (PMID 28054552, 2017). "This is also the evidence that HK1 and HK2 are responsible for the accelerated glucose flux in tumor cells." (PMID 28105937, 2016). "Compared to the negative control, miR-497 mimic significantly inhibited growth of HK1/EBV, HK1, and CNE1 cells (left, middle, right, respectively), suggesting that miR-497 has a tumor-suppressive function." (PMID 26486082, 2015). "In this study, we systematically analyzed the expression profiles of key glycolytic enzymes in patients and mice with HC and found that expression of HK1 and PKM2 was markedly increased and correlated with tumor progression." (PMID 26576639, 2015).
tumor (continued). "We found that expression of hexokinase 1 and the M2 splice isoform of PK (PKM2) was upregulated in HC tissues and that this expression correlated with tumor recurrence and outcome." (PMID 26576639, 2015). "All three genes investigated, GLUT1, HK1, and HK2 as well as the normalizing gene β-actin were detected in all tumor and normal samples." (PMID 26824929, 2013). "Tumours were explanted from mice given 5 × 106 or 8 × 106 GIST882 cells and subjected to verification of hK1 expression by ELISA and immunohistochemistry." (PMID 20859288, 2010). "The orchestration of aerobic glycolysis regulation involves transcription factors, wherein miR-30d modulates the expression of Solute carrier family 2 member 1(SLC2A1) and Hexokinase 1(HK1) via the transcription factor RUNX1, thereby restraining tumor progression." (PMID 39791162, 2025). "HAMLET sensitivity was further modified by the glycolytic state of tumor cells as glucose deprivation sensitized tumor cells to HAMLET-induced cell death and in the shRNA screen, hexokinase 1 (HK1), 6-phosphofructo-2-kinase/fructose-2,6-biphosphatase 1 and HIF1α, modified HAMLET sensitivity." (PMID 38360830, 2024). "Tumor cells largely express the HK2 subtype, which has a high affinity for glucose to ensure it enters the glycolysis process efficiently, whereas normal cells largely express the HK1 subtype." (PMID 37190313, 2023). "Besides, HSC-derived EVs also contained C-X-C motif ligand 10 (CXCL10), hexokinase 1 (HK1), vascular endothelial growth factor (VEGF), matrix metalloprotein 2 (MMP2) and MMP9, which facilitated tumor growth and transfer, as well as angiogenesis." (PMID 37180779, 2023). "The HK1 and HK2 proteins are both highly expressed in KRAS-mutant mouse lung tumors, while the activation of HK2 but not HK1 is inevitable for tumor initiation and progression." (PMID 36532721, 2022). "This suggests that in the absence of RB1 and low HK1, the Rb tumor cells acquire an ability to replenish the TCA cycle, even when glucose-derived pyruvate levels are low." (PMID 36291051, 2022). "HK1 showed weak signals in advanced (n = 15) and non-advanced Rb (n = 10) tumor areas (IHC score = 0–1), while strongly staining the intact retina portions within non-advanced Rb tissues, thereby serving as an internal control." (PMID 35626705, 2022). "The NAD+/NADH ratios and L-carnitine levels indicate that in the absence of RB1 and HK1, tumor cells can flexibly utilize alternate fuels such as glutamine or fatty acids to feed OXPHOS, fulfilling their bioenergetic demands." (PMID 36291051, 2022). "Differential effects of 4EBP1-4A on the translation of HK1 and HK2 suggest that 4EBP1 may regulate glucose and insulin metabolism to inhibit tumor growth, and this needs to be explored." (PMID 35626002, 2022). "When HK1 was also knocked out specifically in HSCs, deletion of Nur77 no longer influenced tumor growth." (PMID 36192599, 2022). "Tumor tissues with high c-Met expression level in TCGA have increased expression of H6PD, PDK2, PDK4, PDPR, PKLR, SLC2A2 genes whereas decreased expression of GYS1, HK1, HK2, SLC2A1, significantly." (PMID 34059694, 2021). "Since HK1 functions as a housekeeping gene in normal tissue and HK2 is upregulated in most aggressive tumors, this distinction makes the SENP1-HK2 axis an excellent target for tumor therapy." (PMID 33753739, 2021). "Moreover, the high expression of HK1, PFKM, and GAPDH genes correlated with the tumor degree of malignancy." (PMID 34573317, 2021). "Recently, hexokinase 1 (HK1) was shown to be a K-RAS4A effector, which could impact on the tumours’ cells metabolism." (PMID 34604308, 2021). "So far, we have proved that YTHDC1-induced miR-30d may function as a tumor suppressor gene by negatively regulating RUNX1 and its downstream glycolytic genes including HK1, and SLC2A1." (PMID 34021267, 2021).
tumor (continued). "Indeed, HIF1α is associated with the up-regulation of several genes directly related to the glycolytic pathway such as glucose transporters (e.g., GLUT1, GLUT3) and glycolytic enzymes (e.g., HK1, HK2), promoting glycolytic flux and tumor development." (PMID 33374292, 2020). "In addition to HK1, there are three other enzymes of HK identified, out of which hexokinase 2 (HK2) is the major enzyme that is closely involved in tumor cell glycolysis." (PMID 31850189, 2019). "Due to its lower Km for glucose, HK1 rather than HK2 is required for tumour cell survival when glucose is scarce." (PMID 28054552, 2017). "Interestingly, we found that HK1 and HK2 can distinctively regulate the adaption of tumour cells to different energy status." (PMID 28054552, 2017). "Our results confirm that HK1 and HK2 are involved in tumor growth maintenance." (PMID 28105937, 2016). "In this study, we aimed to investigate whether hK1 is expressed and released by GIST and participates in tumour growth and expansion." (PMID 20859288, 2010). "At the mechanistic level, histone lactylation promotes the expression of the glycolysis-related gene hexokinase 1 (HK-1) while inhibiting the expression of the gene isocitrate dehydrogenase three non-catalytic subunit γ (IDH3G), maintaining mitochondrial homeostasis and driving tumor progression." (PMID 40589733, 2025). "However, studies have demonstrated that the knockdown of HK2 alone does not inhibit in vivo tumor progression with reduced glucose consumption, suggesting that HK1 compensates for the overall tumorigenic potential." (PMID 37109475, 2023). "Although analysis of cell lines from the CCLE collection revealed that most HCC cell lines express only HK2 and not HK143,44, we found that HCC cells hijacked lEV HK1 secreted from activated HSCs to enhance their proliferation, reflecting the resourcefulness of tumor cells." (PMID 36192599, 2022). "Thus, in the absence of a functional Rb or reduced HK1, these tumor cells produce higher amounts of ATP through increased mitochondrial respiration fed by multiple fuel sources such as glutamine and fatty acids." (PMID 36291051, 2022). "In summary, our results suggest that one of the tumor-suppressive effects of increased expression of miR-30d is to inhibit RUNX1 and inactivate the aerobic glycolysis signaling, forming a vigorous YTHDC1-miR-30d-RUNX1-SLC2A1/HK1 axis to repress PDAC occurrence and progression." (PMID 34021267, 2021). "The dependency of embryonal‐like HB tumor cells on hexokinase 1, as well as the GLUT3, LDHB, and G6PC staining on tumor sections could be used as novel biomarkers to highlight metabolic variation in HB and guide future therapies based on metabolic vulnerabilities." (PMID 28923827, 2017). "Such enhanced utilization of OXPHOS results in greater mitochondrial activity and higher ATP generation in tumor cells lacking RB1 and HK1." (PMID 36291051, 2022). "Taken together, this study demonstrates that knockdown of the glycolytic enzyme HK1 but not HK2 results in the deregulation of energetic metabolism via increased HK2 expression and accelerates tumor malignancy through inducing an EMT phenotype." (PMID 29721175, 2018). "In this study we build on our prior work to show that HK2, but not the other brain-specific isoforms of hexokinase, HK1 and HK3, drives tumor metabolism in GBM." (PMID 27588472, 2016). "Expression of HK1 and PKM2 protein was markedly higher in tumor than in noncancerous tissue samples." (PMID 26576639, 2015). "Immunohistochemical analysis found that HK1 and PKM2, but not PFKB expression, was higher in tumor than in normal tissue samples." (PMID 26576639, 2015). "The decrease in FDG uptake was paralleled by decreases in GLUT1 and HK1 expression, whereas no change in HK2 expression was observed suggesting that GLUT1 and HK1 are involved in the FDG uptake in this tumor model." (PMID 24386456, 2013).
tumor (continued). "Therefore, in the present study, we investigated the HK1, PFKB, and PKM2 expression statuses in HC samples and cells and found that HK1 and PKM2 expression but not PFKB expression was higher in tumor than in normal tissue samples." (PMID 26576639, 2015).